STAT3 (signal transducer and activator of transcription 3)
Diseases named in the same sentence as STAT3 in open-access papers (continued):
Sharing a sentence is not in itself a finding about the gene and the disease.
Obesity (continued). "In these regions, leptin signaling is mediated by the JAK2/Stat3 pathway, in which several negative regulators of JAK2, including SOCS3 and PTP1B, have been reported to promote obesity, supporting the notion that JAK2 inhibitory molecules increase risk for leptin resistance and obesity." (PMID 32630697, 2020). "The lack of STAT5 in the central nervous system causes to obesity with hyperphagia, whereas STAT5 activation in hypothalamic neurons suppresses food intake, suggesting that not only STAT3, but the JAK2-STAT5 pathway also contributes to the prevention of obesity." (PMID 31141984, 2019). "Altogether, the majority (but not all) of studies showed no change or increase in cardiac STAT3 phosphorylation, expression and/or activation in animal models of experimental obesity and/or hyperlipidemia." (PMID 30424579, 2018). "Importantly, they identified STAT3 as the driver of HCC progression in obesity, whereas obesity-driven NASH and fibrosis depend on STAT1." (PMID 30591653, 2018). "In summary, we propose for the first time a new working model showing that transcription factors, such as STAT3, NFκB and EGR1, increase transcript levels of various miRNAs that are unique to the four HRDs (atherosclerosis, NAFLD, obesity, and T2DM/IR) as well as shared among the HRDs." (PMID 30369883, 2018). "Experimental results demonstrated that dietary supplementation of EGCG significantly inhibited HFD-induced obesity by enhancing BAT thermogenesis, and attenuated the hypothalamic inflammation and microglia overactivation by regulating the NF-κB and STAT3 signaling pathways." (PMID 30400620, 2018). "Likewise, mice overexpressing a constitutively active version of STAT3 in POMC neurons show elevated SOCS3 expression and develop obesity as a result of hyperphagia and decreased POMC expression accompanied by central leptin resistance." (PMID 28270795, 2017). "Previous studies reported that negative feedback regulators of JAK2/STAT3 signal transduction increase with obesity." (PMID 27375555, 2016). "Thereby, mice expressing a constitutively active version of signal transducer and activator of transcription 3 (STAT3) selectively in hypothalamic neurons of the arcuate nucleus are lean and resistant to diet-induced obesity, a phenotype arising from increased locomotor activity." (PMID 27589235, 2016). "On the basis of the enhanced AA content found in obesity and CRC, we therefore investigated whether this pro-inflammatory PUFA might affect the activation of STAT3 and PPARγ." (PMID 27494857, 2016). "These isoforms activate JAK2, but not STAT3 signaling, and, as such, are not involved in the anti-obesity effects of leptin." (PMID 27375555, 2016). "Because we previously showed that STAT3 is a substrate of protein tyrosine phosphatase receptor T (PTPRT), we investigate here whether PTPRT regulates food intake and obesity in mice." (PMID 24949727, 2014). "Obesity and lack of breastfeeding following full-term pregnancy both appear lead to greater acute and chronic localized inflammation within the mammary gland related to macrophage infiltration, changes in epithelial cell population, and STAT3 activation." (PMID 39525621, 2024). "We found increased activation of MAPK/ERK, JAK2/STAT3, and PI3k/AKT signaling pathways in human leiomyoma cells as a result of adipocyte coculture, outlining the pathophysiological link between adipocyte hypertrophy in obesity and the development of uterine leiomyoma." (PMID 36771423, 2023). "However, in obesity, STAT-3 signaling can induce HCC in a way independent of recruitment of T cells and evolution of NASH and fibrosis." (PMID 36457551, 2022). "However, the regulatory mechanism supporting the cascade amplification of IL-6/STAT3 pathway related to obesity in CRC is still not fully elucidated." (PMID 36266267, 2022).
Obesity (continued). "Since the incidence of obesity-related HCC is much higher in men than in women, androgen receptors may produce ontogenetic efficacy through alternative mechanisms, such as interaction with signal transducer and activator of transcription 3 (STAT3)." (PMID 34745420, 2021). "Moreover, bulk RNA-Seq revealed an enhanced transcriptional response to LPS at T3 relative to T1 in the lean subjects relative to those with obesity marked by higher expression of pro-inflammatory molecules (IL6, IL1B, TNF) and induction of transcription factors (RELA, IRF1, STAT3)." (PMID 34195568, 2021). "Hence, obesity creates a pro-inflammatory environment that is believed to favor the incidence of several cancers through numerous signal transduction pathways, including the JAK/STAT3 pathway." (PMID 33801973, 2021). "This may be at least one molecular mechanism involved in the reduced B cell function in individuals with obesity, as it induces the secretion of pro-inflammatory cytokines (IL-6/TNF-α) in human peripheral blood B cells through activation of JAK2/STAT3 and p38MAPK/ERK1/2 signaling pathways." (PMID 33760825, 2021). "Moreover, STAT3, MCL1, PMAIP1, SOD2, FOXO3, FOS, FKBP5 may play an essential role in the genesis and growth of obesity and might serve as a possible therapeutic target." (PMID 34712134, 2021). "Therefore, the TCPTP ‘feed-fast switch’ appears to be abrogated in obesity, which could promote elevated TCPTP expression and subsequent STAT3 dephosphorylation, even in the fed state, thereby further promoting obesity." (PMID 34502119, 2021). "However, it is unclear whether FNDC5 is involved in cardiac fatty acid oxidation during obesity, and the crosstalk between PPAR-α and JAK2/STAT3 signaling or other signal transduction molecules needs further investigation." (PMID 30940158, 2019). "Furthermore, impairments in leptin-induced STAT3 phosphorylation were demonstrated in a mouse model of diet-induced obesity following a peripheral, but not central injection of leptin." (PMID 27375555, 2016). "Since leptin is directly correlated with obesity and cancer progression, and activates the JNK/STAT3-signaling pathway, we investigated whether leptin and the respective JNK/STAT3-signaling pathway play some role in modulating the expression of mitochondrial or glycolytic genes." (PMID 26472027, 2015). "However, since reduction in VAT Treg cells was correlated with HFD-induced obesity, and mice lacking STAT3 in T cells gained less body and VAT weights when fed HFD, it is hard to exclude the possibility that the increase of VAT Treg cells is a secondary effect of weight loss in these mice." (PMID 30323806, 2018). "In addition to phosphorylation, leptin-induced STAT3 methylation by protein arginine N-methyltransferase 2 (PRMT2) was also shown to occur, and PRMT2−/− mice are lean, hypophagic, have reduced serum leptin levels and are more resistant to diet-induced obesity (DIO) compared to wild-type littermates." (PMID 28270795, 2017). "Mice lacking SH2B1 display severe obesity, elevated expression of AgRP/NPY, and impaired activation of JAK2 and STAT3." (PMID 38027481, 2023). "PTP-1B, a non-transmembrane PTP, down-regulate leptin/STAT3 signaling via indirectly inactivating JAK2, which may be a new target for the treatment of obesity induced by leptin resistance." (PMID 33849593, 2021).
multiple myeloma (350 papers, 2001 to 2025). "In multiple myeloma, CaMKIIγ is frequently up-regulated and maintains STAT3 and ERK signaling; gain- and loss-of-function studies demonstrate dependence on CaMKIIγ, and berbamine analogs show preclinical efficacy against CaMKIIγ-positive xenografts." (PMID 41283247, 2025). "STAT3 that is persistently active has been associated with various malignancies, though it is most commonly associated with head and neck cancer and multiple myelomas." (PMID 37860678, 2023). "TQ also caused inhibition of STAT3 and NF-kB and their regulatory gene products in U266 multiple myeloma cells and KBM-5 human myeloid cells, respectively." (PMID 36498999, 2022). "The experimental and clinical evidence reviewed herein suggests a key role for STAT3 in favoring several “hallmark of cancer” traits in the pathogenesis of multiple myeloma." (PMID 35326392, 2022). "For example, activated FAK/Syk/Akt/mTOR and STAT3 pathways are known to underlie Reelin-driven cancer cell growth and metabolic reprogramming, including glycolysis in myeloma cells." (PMID 35379785, 2022). "STAT3 is considered a proto‐oncogene and constitutive activation of STAT3 is implicated in the development of various cancers, including multiple myeloma, leukaemia and lymphomas." (PMID 33382511, 2021). "STAT3 is implicated in the onset and progression of human cancers including multiple myeloma, leukaemia, lymphomas and solid tumours." (PMID 33382511, 2021). "Activation of STAT3 has been found to be associated with shorter survival of patients with multiple myeloma." (PMID 31058086, 2019). "Here, we demonstrate for the first time that piperlongumine inhibits the STAT3 signal pathway in MM cells by directly binding to the Cys712 residue; a C712A mutation in STAT3 largely reversed the anti-myeloma effects of piperlongumine." (PMID 27634873, 2016). "Constitutively activated STAT3 has been implicated in multiple cancers such as head and neck cancer, leukemias, lymphomas, and multiple myeloma, making it a potential target for cancer therapy." (PMID 25665066, 2015). "STAT3 is often constitutively activated in various types of human cancer including multiple myeloma and closely associated with cancer cell proliferation and antiapoptosis." (PMID 23818927, 2013). "The Signal Transducer and Activator of Transcription 3 (STAT3) signaling pathway has been implicated in the proliferation, chemoresistance, and survival of multiple myeloma cells." (PMID 20712901, 2010). "Hence, STAiR18 is an important regulator of myeloma cell survival and is strongly associated with the oncogenic function of STAT3." (PMID 32041604, 2020). "We showed that GAC 17:1 treatment causes substantial abrogation of JAK2 phosphorylation level in a time-dependent manner that may be directly implicated in its STAT3 inhibitory effects in multiple myeloma cells." (PMID 28208828, 2017). "In this study, we specifically investigated whether ginkgolic acid can suppress the STAT3 pathway in multiple myeloma cells and the underlying molecular mechanism(s) involved." (PMID 28208828, 2017). "STAT3 activation has also been implicated in decreased survival in patients with multiple myeloma." (PMID 28208828, 2017). "14-3-3ζ is linked to constitutive activation of Stat3 in myeloma cells." (PMID 22279540, 2012). "STAT3 is implicated in cell survival and growth in multiple myeloma cells." (PMID 22260501, 2012). "STAT3 phosphorylation is suppressed by curcumin, blocking its nuclear translocation and transcriptional activity in human multiple myeloma cells." (PMID 41020838, 2025). "In leukemic and myeloma systems, CaMKIIγ sustains NF-κB, β-catenin, STAT3, and ERK signaling, reinforcing stem-like properties and creating a permissive environment for therapy escape." (PMID 41283247, 2025). "In multiple myeloma cells, curcumin suppresses STAT3 phosphorylation, blocking its nuclear translocation and transcriptional activity." (PMID 41020838, 2025).
multiple myeloma (continued). "Both studies in multiple myeloma reported high STAT3 expression and phosphorylation, which was also observed in the resistant PC-3 RB40." (PMID 40699751, 2025). "Preclinical study in multiple myeloma models revealed that FT suppressed the STAT3/5-DNA binding capacity while simultaneously inhibiting the activation of upstream kinases JAK1, JAK2 and Src." (PMID 40841966, 2025). "BBR has previously demonstrated modulations to miR-21 of U266 and RPMI-8266 cells, another IgG-producing myeloma cell line, potentially through IL-6/STAT3, and the consequential increase in programmed cell death 4 gene expression." (PMID 41294852, 2025). "A synergistic relationship of STAT3-targeting and cladribine has so far only been described in multiple myeloma." (PMID 40234614, 2025). "Arsenic acid has been shown to inhibit STAT3 activation in myeloma cells 39, consequently reducing IL-6 release." (PMID 40386065, 2025). "Research has identified miR-451a as a regulator of the IL6R gene and an activator of the JAK2/STAT3 pathway, which regulates the proliferation and apoptosis of multiple myeloma cells." (PMID 39129166, 2025). "In U266 myeloma cell lines, blocking STAT3 signaling via a JAK family kinase activity inhibitor (AG490) inhibited Bcl-XL expression and induced apoptosis." (PMID 38339245, 2024). "In multiple myeloma cells, betulinic acid suppressed constitutive stimulation of STAT3, Src kinase, JAK1, and JAK2." (PMID 38397437, 2024). "Consistently, the FXR agonist GW4064 was reported to increase STAT3 activation in endometriotic stromal cells, whereas FXR inhibitor Z-GS treatment suppressed both STAT3 phosphorylation and activities in multiple myeloma cells." (PMID 38360812, 2024). "Additional research revealed that by preventing the phosphorylation of the upstream kinase Src, TQ reduced the constitutive phosphorylation and DNA binding activity of signal transducer and activator of transcription-3 (STAT3) in skin cancer and myeloma." (PMID 38397437, 2024). "Previous studies have shown that TP can exert anticancer effects by down-regulating STAT3 signaling in various cancer cells, such as ovarian, colon, lung, and multiple myeloma cells." (PMID 38731894, 2024). "Withaferin A, the main withanolide in W. somnifera, modulated TGF-β (Transforming growth factor-β) signaling in endometrial cancer and suppressed STAT3 (signal transducer and activator of transcription 3) in multiple myeloma and neuroblastoma." (PMID 38303989, 2024). "For instance, using immunoglobulin E (IgE) producing myeloma (U266 cells), sophorolipids extracted from Candida bombicola decreased IgE and gene expression levels of STAT3, TLR-2, and IL-6." (PMID 36441210, 2023). "BOR can suppress phosphorylation of STAT3 induced by IL-6 via myeloma cells and bone marrow stromal cell binding." (PMID 38004369, 2023). "The induction of miR-21 via STAT3 is noted in multiple myeloma cells, while STAT3-mediated suppression of miR-199a-5p occurs in cardiomyocytes and endothelial cells." (PMID 37759631, 2023). "Western blot analysis of the mTOR and STAT3 survival pathways showed a significant reduction in p‐mTOR and p‐STAT3 in both LP‐1 and XG‐2 multiple myeloma cells treated with propranolol." (PMID 36245401, 2023). "AR-42 (previously known as OSU-HDAC42; Arno Therapeutics) has been shown to have potent HDAC-inhibitory activity, which inhibit the GP130/STAT3 pathway to inhibit multiple myeloma cell growth." (PMID 36977736, 2023). "Azaspirane-like molecules, specifically atiprimod, inhibit myeloma cell proliferation by modulation, which involves blocking the phosphorylation of key proteins, such as STAT3, with a maximum inhibition at 20 μM." (PMID 37299000, 2023). "Stat3 is often constitutively active in many human cancer cells, including multiple myeloma, leukemia, lymphoma, and solid tumors." (PMID 37089712, 2023).
multiple myeloma (continued). "Arctiin has been reported to inhibit STAT3 phosphorylation at the tyrosine 705 residue and has shown potential in treating human multiple myeloma cells." (PMID 37701157, 2023). "The goal of this study was to characterize the relationship between ATR and STAT3 interactions in human multiple myeloma (MM) cells." (PMID 37126127, 2023). "In conclusion, radotinib inhibits multiple myeloma cell proliferation via suppression of STAT3, JAK2 and c-Myc signaling." (PMID 35503759, 2022). "Multiple Myeloma: curcumin prevents IL-6-induced STAT3 phosphorylation and subsequent STAT3 nu-clear translocation." (PMID 36712505, 2022). "CD163-expressing TAMs displayed elevated levels of pSTAT3 and correlated to poor prognosis in 77 patients with myeloma from STAT3 is over-activated within CD163pos bone marrow macrophages in both Multiple Myeloma and the benign pre-condition MGUS." (PMID 36686729, 2022). "Myeloid cell leukemia 1 (Mcl-1), a signal transducer and activator of transcription 3 (STAT3)-regulated molecule, is necessary for myeloma cell survival." (PMID 35637953, 2022). "The BM microenvironment (niche) has recently been recognized as essential for myeloma development and chemoresistance by constitutive activation of STAT3 signaling." (PMID 35326392, 2022). "Thymoquinone, in combination with thalidomide and bortezomib, enhanced the apoptotic effect of the drugs in multiple myeloma (MM) cells through the inhibition STAT3 signaling pathway." (PMID 35267408, 2022). "In multiple myeloma (MM), arctiin blocked the STAT3 phosphorylation of tyrosine 705 by activating tyrosine phosphatase ε (PTPε)." (PMID 35761235, 2022). "Baicalein not only inhibited IL-6-mediated phosphorylation of JAK, STAT3, and AKT, but also repressed STAT3-driven upregulation of BCL-XL in multiple myeloma cells." (PMID 35955525, 2022). "A high HO-1 expression level in bone marrow stromal cells can trigger multiple resistances by targeting the JAK2/STAT3 pathway in myeloma." (PMID 36428612, 2022). "STAT3 that is constitutively active is found in many types of cancer, such as neck/head, lymphomas, and multiple myeloma, as well as leukemia." (PMID 36080130, 2022). "Curcumin-induced inhibition of STAT3 phosphorylation not only suppressed the growth of myeloma cells, but also sensitized MM cells to dexamethasone." (PMID 35153791, 2022). "Study reported that lncRNA nuclear-enriched abundant transcript 1(NEAT1) sponged miR-214 to target regulation B7-H3 thereby promoted M2 macrophage polarization via phosphorylating JAK2/STAT3 signaling in multiple myeloma." (PMID 36153596, 2022). "Constitutive and sustained activation of STAT3 has been observed in many human solid and hematological cancer cells, including lung, breast, colon, leukemia, multiple myeloma, and lymphoma." (PMID 35503759, 2022). "Thymoquinone has the potential to inhibit IL-6 induced STAT3 activation in multiple myeloma (MM) cells (U266 and RPMI8226), followed by blocking JAK and SRC, resulting in the suppression of the downstream signaling pathway." (PMID 35267408, 2022). "For this reason, many researchers are participating with great interest in the research that STAT3 can be a novel molecular biological target in many cancers, including multiple myeloma." (PMID 35503759, 2022). "Another study showed elevated CKS1B promoted myeloma cell drug resistance by activation of STAT3 signaling." (PMID 32960462, 2021). "It was recently shown that STAT3 can also regulate the expression of the cancer-related miR-21 in multiple myeloma." (PMID 34638550, 2021). "STAT3 is constitutively activated during the onset and progression of a variety of cancers, including multiple myeloma, leukaemia, lymphomas and solid tumours." (PMID 33382511, 2021). "Previous studies have shown that SOCS3 inhibits the JAK2/STAT3 pathway in hepatocyte and multiple myeloma cells." (PMID 34765550, 2021).